LPL (lipoprotein lipase)
Diseases named in the same sentence as LPL in open-access papers (continued):
Sharing a sentence is not in itself a finding about the gene and the disease.
atherosclerosis (continued). "Also, VEGF-A decreases the activity of LPL (plasma lipoprotein lipase), resulting in the accumulation of triglycerides in large lipoprotein granules, including chylomicrons and very low-density lipoprotein, which resulted in the change of atherosclerosis promotion." (PMID 35055117, 2022). "Based on genetically modified mouse models, such as LPL−/−, GPIHBP1−/−, and ApoC3 transgenic mice, triglycerides were demonstrated to promote atherosclerosis." (PMID 34796210, 2021). "This study was designed to determine the effects of miR-590 on lipoprotein lipase (LPL) expression and development of atherosclerosis in apolipoprotein E knockout (apoE−/−) mice and explore the potential mechanisms." (PMID 26397958, 2015). "RCT is considered to be the primary mechanism through which HDL protects against atherosclerosis, but its production is limited in LAD patients by LPL down-regulation and PLTP up-regulation." (PMID 19134193, 2009). "One study demonstrated that the induction of lipoprotein lipase (LPL) by the non-coding RNA HDAC11-AS1 may be mediated by adropin, leading to a reduction in atherosclerosis in mice." (PMID 39766320, 2024). "Conversely, hydrolysis by LPL generates VLDL particles, IDL particles, and CM remnants which transport significant quantities of cholesterol molecules into the arterial intima, leading to a pronounced degree of atherosclerosis." (PMID 38968507, 2024). "Moreover, hydrolysis of triglycerides in TRLs by lipoprotein lipase can liberate NEFA, inducing inflammation, promoting atherosclerosis." (PMID 38413437, 2024). "Literature shows that VLDL concentrations are related directly or indirectly in the development of atherosclerosis; for example the fatty acid composition of VLDL is critical for the activity of lipoprotein lipase and the formation of proatherogenic LDL and VLDL remnants." (PMID 33255353, 2020). "Likewise, animal models convincingly show that increased clearance of TRLs and RLPs by LPL activation (achieved by inhibition of APOC3, ANGPTL3, or ANGPTL4 action, or increased APOA5) results in protection from atherosclerosis." (PMID 32849290, 2020). "Thus, LPL and BMP7, which are associated with insulin and glucose homeostasis, and MCP2 and SST, which are associated with regulation of immune system processes and cell migration, may play important roles in both the formation and regression of atherosclerosis." (PMID 30958112, 2019). "Specific deletion of macrophage LPL (with no changes in total plasma LPL activity) significantly reduced atherosclerotic lesions in Apoe−/− mice, supporting an important role for macrophage LPL in atherosclerosis." (PMID 39081272, 2024). "As TG contents are gradually degraded by lipoprotein lipase in the bloodstream, the cholesterol in RLP-C could also be involved in atherosclerosis plaque formation and subsequent cardiovascular events, and it has been recognized as more atherogenic and proinflammatory than the cholesterol in LDL-C." (PMID 34174876, 2021). "To date, however, it is still not clear whether miR-27 plays a role in the development of atherosclerosis through targeting macrophage LPL in vivo." (PMID 27257686, 2016). "Interestingly, LPL (lipoprotein lipase, 1,001 fold), APOE (apolipoprotein E, 778 fold), FABP4 (fatty acid binding protein 4, 680 fold), and APOC1 (apolipoprotein C–I, 614 fold) are atherosclerosis related genes in which activated monocytes play a role." (PMID 23844045, 2013). "P-407 is a nonionic surfactant that has been found to inhibit lipoprotein lipase, an enzyme involved in the hydrolysis of triglycerides, and to enhance the activity of 3-hydroxy-3-methyl-glutaryl-coenzyme A (HMG-CoA) reductase, resulting in acute hyperlipidemia that can cause atherosclerosis." (PMID 37765165, 2023). "Thus, although we still do not know whether LPL acts to enhance or inhibit atherosclerosis, we are certain that it plays a crucial role in atherogenesis." (PMID 30959963, 2019).
atherosclerosis (continued). "In vascular subendothelium, macrophage-derived LPL may contribute to foam cell formation and the progression of atherosclerosis via a nonenzymatic bridging role that modulates the cell surface accumulation and subsequent cellular uptake of modified lipoproteins especially ox-LDL." (PMID 27257686, 2016). "Another interesting perspective is that in Apoe−/− mice with or without LPL overexpression, non-HDL cholesterol levels are similar, yet the atherosclerosis is suppressed." (PMID 32849290, 2020). "Lipoprotein lipase (LPL) is upregulated in atherosclerotic lesions and it may promote the progression of atherosclerosis, but the mechanisms behind this process are not completely understood." (PMID 32437392, 2020).
hyperlipidemia (138 papers, 2006 to 2026). "Muparfostat exhibits additional binding affinity toward lipoprotein lipase, thereby causing severe hyperlipidemia and ultimately exacerbating hepatic steatosis and liver damage, particularly in obese individuals." (PMID 39611414, 2025). "P-407 is a surfactant block copolymer that causes dose-dependent hyperlipidemia by inhibiting lipoprotein lipase (LPL), which is needed to degrade triglycerides into fatty acids." (PMID 40558641, 2025). "LPL is highly expressed in coronary artery disease patients and a variant of LPL is closely related to hyperlipidemia." (PMID 39598239, 2024). "Given the genetic predisposition, relevant genetic and lipid examination was conducted on his parents as well, and his father was found to have the same LPL gene mutation and hyperlipidemia." (PMID 38975277, 2024). "LPL is a key enzyme regulating lipid fuel processing, and decreased levels or activity can alter LPL lipolytic function, leading to hyperlipidemia and metabolic disorders in the body, causing damage to the vascular endothelium." (PMID 38390206, 2024). "With severe diabetes, animals developed hyperlipidemia that was associated with a reduction in heparin-releasable LPL activity in the heart." (PMID 39081272, 2024). "Genetic mutation and polymorphism on ApoA-1, ApoE, and LPL is also closely related to hyperlipidemia according to previous research by Baroni, 2003." (PMID 39598239, 2024). "A crucial factor inOSA-associated hyperlipidemia is the impaired impaired clearance of circulatinglipoproteins due to disrupted lipoprotein lipase (LpL) function." (PMID 39076499, 2024). "Corticosteroids upregulate hormone‐sensitive lipase and lipoprotein lipase thus promoting lipolysis, and prednisolone causes hyperlipidemia in healthy cats." (PMID 38485220, 2024). "Variant c.953A>G in the LPL gene is frequently reported in patients with familial combined hyperlipidemia and is therefore identified as pathogenic." (PMID 35741760, 2022). "Deficiencies in LPL play an important role in the pathophysiology of hyperlipidemia in diabetes and the treatment with insulin increases PLP activity thus causing a fall in plasma triglycerides." (PMID 35620400, 2022). "Mutations that cause LPL deficiency are highly associated with hyperlipidemia and various lipoprotein metabolic disorders." (PMID 36419087, 2022). "In the present study, we attempted to depict the underlying mechanism by which GLXBBX improves hyperlipidemia induced by P407 based on the interaction between lipid-lowering and LPL activity." (PMID 34036306, 2021). "Mutations in the LPL gene or its decreased transcriptional activity lead to the development of hyperlipidemia." (PMID 32121067, 2020). "In STZ-induced diabetes, insulin drop caused the failure of lipoprotein lipase to perform normal physiological functions, which leads to hyperlipidemia and hypercholesterolemia." (PMID 32967670, 2020). "For example, mice with Sel1L deficiency in adipocytes exhibit lipodystrophy and hyperlipidemia due to the ER retention of lipoprotein lipase (LPL)." (PMID 29457782, 2018). "For example, Chang and his colleagues first reported that in HTG-induced AP patients, lipoprotein lipase gene mutation was significantly increased, and the probability of AP was 77.8% in patients with hyperlipidemia caused by the mutation in this gene." (PMID 25887309, 2015). "LOC284100 and CEACAMP8 are associated with LPL mRNA expression, while hyperlipidemia is one common complication of preeclampsia." (PMID 24312300, 2013). "For example, lopinavir binds to lipoprotein receptor related protein (LPR), impairing hepatic chylomicron uptake and triglyceride clearance by LPR –lipoprotein lipase complex, causing hyperlipidaemia." (PMID 23098156, 2012). "LPL deficiency leads to hyperlipidaemia, which is characterized by the pathological presence of chylomicrons, together with elevated VLDL after a 12–14 hour fast similar to what we observed in F1B hamsters." (PMID 18070363, 2007).
hyperlipidemia (continued). "A large number of studies have been performed on the association between three, functionally active single nucleotide polymorphisms (SNPs) in the LPL gene, namely D9N, N291S and S447X and hyperlipidemia." (PMID 17727701, 2007). "The aim of this study was to investigate the role of the LPL S447X polymorphism in a sample of subjects with combined hyperlipidemia and compare them with healthy controls." (PMID 16822320, 2006). "Mice with APOA5 deficiency develop hyperlipidemia with reduced post-heparin plasma LPL activity." (PMID 40806668, 2025). "No thrombophilia-related gene mutation was detected, but a heterozygous mutation in lipoprotein lipase (LPL) gene (c.547G > A) was identified, which is associated with autosomal recessive inheritable LPL deficiency, indicating a high likelihood of hyperlipidemia." (PMID 38975277, 2024). "Finally, LPL variant rs118204057 has multiple reports associated with hyperlipidemia and hyperlipoproteinemia pathology and protein function." (PMID 37065472, 2023). "In addition, estrogen can regulate some risk factors for CHD, such as hypertension and hyperlipidemia, by reducing the vasoconstrictor endothelin and increasing the activity of lipoprotein lipase to prevent CHD and HF." (PMID 38250027, 2023). "The risk of diabetes and hyperlipidemia was higher in summer, which may be related to higher lipoprotein lipase activity." (PMID 38031031, 2023). "In addition, triton is known to cause hyperlipidemia through several mechanisms, mainly by inhibiting lipoprotein lipase activity, which can result in the blockage of TG-rich lipoproteins clearance." (PMID 32308705, 2020). "In this study, AE as well as NAOEAE treatments could attenuate hyperlipidemia caused by fructose consumption probably by increasing LPL activity." (PMID 28798859, 2017). "An examination of the mechanism underlying P-407-induced hyperlipidemia demonstrated marked alterations in the activities of plasma hepatic lipase (EC 3.1.1.3) and lipoprotein lipase(EC 3.1.1.34), which belong to members of the α/β hydrolase fold family similar to CES (EC 3.1.1.1)." (PMID 24699684, 2014). "Hyperlipidemia is a risk factor of arteriosclerosis, stroke, and other coronary heart disease, which has been shown to correlate with single nucleotide polymorphisms of genes essential for lipid metabolism, such as lipoprotein lipase (LPL) and apolipoprotein A5 (APOA5)." (PMID 29425239, 2018). "Type I hyperlipidemia is characterized by severely elevated levels of chylomicrons, and thus high circulating levels of cholesterol and especially triacylglycerols, and is caused by mutations of either the gene for lipoprotein lipase or its cofactor apolipoprotein C-II." (PMID 30297656, 2018). "Pro-inflammatory cytokines such as IL-1β, TNF-α, and IL-17 disrupt systemic lipid homeostasis by suppressing lipoprotein lipase and promoting hepatic lipogenesis, leading to hyperlipidemia." (PMID 41508030, 2026). "Under physiological conditions, LPL efficiently decomposes plasma triglycerides, but its activity is often compromised in hyperlipidemia." (PMID 41244823, 2025). "Nevertheless, it is important to acknowledge that the Triton WR-1339-induced hyperlipidemia model, although well-established and commonly employed in preclinical studies, induces lipid abnormalities acutely by inhibiting lipoprotein lipase." (PMID 40938933, 2025). "Preclinical evidence shows that enhancing LPL activity improves triglyceride clearance and lipid profile modulation, underscoring its therapeutic potential in hyperlipidemia." (PMID 41244823, 2025).
hyperlipidemia (continued). "Others include modulating enzymes like lipoprotein lipase, glucose‐6‐phosphatase, lactate dehydrogenase, and aldose reductase; and improvement of hyperlipidemia, renal function, and other diabetic complications." (PMID 41019174, 2025). "This study revealed that reduced serum HL and LPL activity in model mice impaired triglyceride catabolism, leading to lipid accumulation and exacerbation of hyperlipidemia." (PMID 41244823, 2025). "Regulation of LPL and HL activity is critical for maintaining lipid metabolic balance, with their dysregulation contributing to hyperlipidemia pathogenesis." (PMID 41244823, 2025). "Acc−/− mice with decreased lipoprotein lipase (LPL) activity have reduced TG clearance leading to hyperlipidemia." (PMID 40552158, 2025). "Previous attempts to modulate LPL activity using small molecules produced highly significant effects in several animal models of hyperlipidemia." (PMID 38455763, 2024). "Compound III is described as an LPL activator and effective in the prevention and treatment of hyperlipidemia and obesity." (PMID 38455763, 2024). "Compared with the hyperlipidemia group, the expression of LPL significantly increased after administration of different doses of UAG (P<0.01)." (PMID 38164484, 2024). "From the aspect of the molecular level, ApoA-1, ApoE, and lipoprotein lipase (LPL) genes are related to hyperlipidemia." (PMID 39598239, 2024). "Diseases connected to lipid metabolism, like hyperlipidemia and fatty liver disease, are impacted significantly by LPL." (PMID 38339301, 2024). "TNF-a can inhibit the lipogenic activity of several lipases, including LPL, inhibit lipid synthesis and reduce LPL mRNA expression, while leading to hyperlipidaemia." (PMID 37533569, 2023). "Triton WR-1339 induces oxidative reactions and prevents the catabolism of triacylglycerol-rich lipoproteins by lipoprotein lipase (LPL) to induce hyperlipidemia." (PMID 37389221, 2023). "Abnormal lipoprotein lipase (LPL) activity is considered to be one of the mechanisms leading to PNS hyperlipidemia." (PMID 35399079, 2022). "On the one hand, its presence appears to slow LPL-mediated hydrolysis of VLDL TG—presumably favoring hyperlipidemia." (PMID 34863862, 2022). "Oral administration of red ginseng acidic polysaccharide (RGAP) dose-dependently upregulates the LPL activity of hyperlipidemia rats and reduces the level of TG to regulate the hyperlipidemia state of rats." (PMID 35335266, 2022). "Poloxamer 407 (P407) has been shown to induce massive hyperlipidemia by directly inhibiting the heparin-releasable fraction of LPL." (PMID 34036306, 2021). "After verification, we found that GLXBBX alleviated hyperlipidemia induced by P407 by activating LPL activity, and GLXBBX inhibited early hepatic steatosis by antagonizing the mRNA overexpression of SCD1, blocking hepatic TG synthesis." (PMID 34036306, 2021). "In conclusion, we provided evidence that GLXBBX treatment effectively attenuates hyperlipidemia by activating LPL activity." (PMID 34036306, 2021). "As an alternative, heparin has been tested and used in the treatment of hyperlipidemias in horses due to its stimulative action upon peripheral utilization of triglycerides and lipoprotein lipase activity." (PMID 34947937, 2021). "Related to pathology, severely diabetic animals with hyperlipidemia showed a decline in heparin-releasable LPL activity at the vascular lumen." (PMID 34356640, 2021). "Investigations on energy metabolic mechanism demonstrates that the hyperlipidemia mitigating capacities of AB-SCF are up-regulated on lipoprotein lipase, AMPK, p-AMPK and down-regulated at fatty acid synthase." (PMID 34867418, 2021). "In this study, LPL mRNA and protein expression in the hyperlipidemia-model rats induced by a high-fat diet were significantly increased and their expression were regulated by the PPAR-signaling pathway." (PMID 34681767, 2021).